TLR4 (toll like receptor 4)
Diseases named in the same sentence as TLR4 in open-access papers (continued):
Sharing a sentence is not in itself a finding about the gene and the disease.
colitis (continued). "An attenuated trend of the expression of p65, pp65, TLR4, STAT3, p-STAT3, JAK2 in TNBS-induced colitis rats was observed in the groups treated with CP." (PMID 30042683, 2018). "Thus, the role of TLR4 during colitis could be either protective or damaging." (PMID 29441063, 2018). "TLR-9 and MBL-C expression increased significantly in response to both C. glabrata and colitis, when compared to mice treated with DSS only, although TLR-4 expression decreased." (PMID 29463799, 2018). "Compared with the normal group, mRNA levels of TLR4, NF-κB, IL-6, STAT3, and JAK2 in colitis rats remarkably increased (P < 0.001, P < 0.01)." (PMID 30042683, 2018). "The relative pp65, TLR4, and p-JAK2 levels in TNBS-induced colitis rats were diminished significantly after treatment of HP, MP, and LP." (PMID 30042683, 2018). "When IRAK1 is suppressed by small molecule treatment, it has been shown to block the TLR4-mediated inflammatory response, as well as DSS- or LPS-induced colitis and septic shock." (PMID 28680194, 2017). "TLR4 dependent signaling of LPS derived from MDR PA differentially mediates both intestinal and splenic immune responses in murine chronic IL10−/− colitis." (PMID 29151895, 2017). "In the colon, however, the interaction of NOD and TLR4 is antagonistic, with NOD2 activation attenuating TLR4-dependent cytokine production and experimental colitis." (PMID 29213271, 2017). "In order to investigate the Toll-like receptor-2 (TLR2), TLR4, and interleukin 10 (IL-10) molecular signaling pathways involved in BF-mediated prevention of dextran sulfate sodium (DSS)-induced colitis." (PMID 28683149, 2017). "We subsequently determined the possible involvement of TLR-4, MyD88 and NF- κB protein expression levels in the anti-UC effects of BR-SMEDDS in DSS-induced colitis mice by Western blotting analysis." (PMID 29078713, 2017). "In this study, we showed that baicalein significantly inhibited the up-regulation of TLR4 and MyD88 in TNBS-induced colitis mice and in LPS-induced macrophages." (PMID 29180692, 2017). "Upon administration of DSS, mice in the WT/GF/DSS, TLR4/GF/DSS, and TLR2/GF/DSS groups developed severe colitis and colitis-related signs (based on colon lengths and fecal occult tests)." (PMID 28683149, 2017). "In another study, it was reported that the attenuated colitis in mice treated with hyaluronic acid was directly correlated with the increased expression of cyclooxygenase 2 (Cox2) and PGE2 production via a TLR4-dependent mechanism." (PMID 25853847, 2015). "In this study, our results have shown that Medilac-S alleviated the protein and mRNA expressions of TLR2, TLR4, and TLR9 in the colon mucosa in experimental colitis." (PMID 25276470, 2014). "Of note, the S. Typhimurium-infected TLR-4−/− mice and the wild-type (C57BL/6) mice infected with C. rodentium exhibited significantly shortened colons, indicating active colitis." (PMID 24465207, 2014). "After the establishment of experimental colitis, the expressions of TLR2, TLR4, and TLR9 were enhanced in the inflammatory cells which were located in lamina propria and submucosa." (PMID 25276470, 2014). "While TLR2 and TLR4 were up-regulated, TLR5 was significantly down-regulated in our TNBS-colitis model." (PMID 23382912, 2013). "The contribution of innate immune activity in IBD carcinogenesis is further suggested by recent research implicating epithelial toll-like receptor 4 (TLR4) as a potential marker for dysplasia and target for preventing CRC in colitis." (PMID 24696788, 2012). "We found that TLR4-mediated induction of COX-2 results in production of both PGE2 and 15d-PGJ2 during the acute phase of colitis." (PMID 24212947, 2011). "Thus, treatment with DSS and TNBS may increase the growth of gram-negative bacteria, produce LPS, and cause colitis via TLR-4-linked NF-kB activation." (PMID 20181058, 2010).
colitis (continued). "Acute C. rodentium-induced colitis in C57BL/6J mice and chronic spontaneous Helicobacter-dependent colitis in TLR4−/− x IL-10−/− mice were utilized for evaluation." (PMID 20976045, 2010). "TLR-4 is potently expressed in intestinal epithelial cells from the colons of patients with IBD and significantly up-regulated during DSS-induced colitis in mice." (PMID 20181058, 2010). "The reduced macroscopic signs of colitis displayed by the DSS-treated TLR2-/-, TLR4-/-, and TLR2/4-/- mice point towards important roles of LPS and TLR2 ligands (such as lipopeptides) in acute inflammatory processes in the colon." (PMID 17653282, 2007). "Because knowledge on shifts in the intestinal microflora during colitis is limited, we performed a global survey of the colon flora of C57BL/10 wild-type (wt), TLR2-/-, TLR4-/-, and TLR2/4-/- mice treated for seven days with 3.5% dextrane-sulfate-sodium (DSS)." (PMID 17653282, 2007). "In contrast, TLR2-/-, TLR4-/-, and TLR2/4-/- animals displayed significantly (P<0.001) lower clinical scores of 7.1±1.6, 7.0±3, and 4.2±2.3, respectively, as compared to wt animals, thus indicating that colitis is exacerbated via TLR2- and TLR4-signaling." (PMID 17653282, 2007). "Consequently, peptides and antibodies that specifically target S100A9 in the colon have shown efficacy in mouse models, reducing both colitis and CAC by inhibiting their interactions with TLR4 and RAGE." (PMID 40565156, 2025). "In a DSS-induced colitis model, we observed that activation of the HMGB1/TLR4/NF-kB pathway resulted in decreased GPX4 expression, accompanied by increased mRNA levels of ferroptosis-related indicators (PTGS2, IREB2, CS, RPL8, and ATP5G3), which was further verified by cellular experiments." (PMID 40689397, 2025). "Acute colitis was induced in wild-type (WT), TLR2 knockout (KO), TLR4 KO, and TLR9 KO mice by administrating the mouse pathogen C. rodentium, then colitis severity was evaluated based on body weight changes, pathology, and mucosal cytokine gene expression at two weeks after infection (acute phase)." (PMID 41293152, 2025). "In normal mice, TA administration increased the expression of TLR4, while in colitis mice, TA did not affect the mRNA levels of TLR2 and TLR4." (PMID 40333150, 2025). "In colitis, CYBB cooperates with TLR4 to regulate the activation of the NLRP3 inflammasome." (PMID 40692778, 2025). "In DSS-induced colitis mouse model, HMGB1 upregulation accompanied by changes in TLR4, NF-κB, and GPX4 expression and ferroptosis-related genes upregulation, while inhibition of HMGB1 attenuated inflammation, restored barrier function, and reversed ferroptosis." (PMID 40689397, 2025). "The findings of the present study revealed that rTs-gal may inhibit signalling pathways that involve enteric bacteria-derived LPS, TLR4, and NF-κB in mice with DSS-induced colitis and attenuate DSS-induced colitis in animals by modulating the gut microbiota." (PMID 38172977, 2024). "Therefore, inhibiting the TLR4/MyD88/COX-2 signaling pathway in present study was shown to be a valuable approach for the prevention and improvement of colitis." (PMID 38611304, 2024). "Additionally, IRF4 acts as a negative regulator of TLR4 signalling by modulating cIAP1/2 ubiquitination and expression of inflammatory cytokines in TNBS‐induced colitis." (PMID 37341064, 2023). "For instance, human umbilical cord blood-derived MSCs could reduce colitis by producing PGE2, and ablation of the TLR4-p38MAPK-Cox2 pathway in MSCs aggravated colitis development." (PMID 37574502, 2023). "Quinic acid ameliorated ulcerative colitis through the inhibition of two TLR4‐NF‐κB and NF‐κB‐INOS‐NO signaling pathways, which results in the reduction of colitis complications, including oxidative stress, inflammation, apoptosis, and histopathological injuries in rats." (PMID 37647443, 2023).
colitis (continued). "Importantly, TNBS treatment enhanced TLR4 and TRPV1 coexpression in primary afferents including the trigeminal sensory neurons and DGR neurons of colitis mice." (PMID 36910013, 2023). "The mechanism(s) by which reduced TLR4 expression contributes to colitis sensitivity are clearly multifaceted and still not entirely understood." (PMID 37768050, 2023). "Despite further studies being needed to confirm this hypothesis, our results provide the first evidence on the ability of micronized PGA to target colitis through a double mechanism of action: PPAR-α agonism and TLR-4 antagonism." (PMID 36009057, 2022). "Regulation of Toll-like receptor 4 (TLR-4) is an intracellular pattern recognition receptor, which plays an important role in response to intestinal epithelial injury and in limiting intestinal bacterial migration in mice with colitis." (PMID 35795556, 2022). "For this review, we searched for relevant articles published between 2011 and December 2021 in PubMed/Medline, using different combinations of key terms including “TLR4”, “inflammatory bowel disease”, “IBD”, “colitis”, “intestinal inflammation”, and “phytochemical”." (PMID 35484567, 2022). "However, Bp7 and Bp8 intervention drastically down-regulated the expression of Tlr4, NF-κB, iNOS, and COX2 and drastically up-regulated the expression of STAT3, Nrf2, and PPARγ in colitis mice (p < 0.05)." (PMID 35681301, 2022). "In addition, ZBE inhibited TNF-α, IL-1β, and IL-12 by regulating the TLR4-and TLR4-related pathways in mice and LPS-induced cellular inflammation in DSS-induced experimental colitis." (PMID 36081930, 2022). "Therefore, we established that the IRAK1/4 inhibitor effectively improves colitis induced by DSS, partly by inhibiting the TLR4/NF-κB pathway, reducing inflammation, and maintaining the integrity of the colonic barrier." (PMID 35699749, 2022). "Consistent with our phenotype, CoHo TLR4−/− and FM(WT)→TLR4−/− recipient mice displayed ameliorated colitis and elevated colonic RORγt+ Treg cells, indicating that colonic suppressive RORγt+ Treg cells mitigated colitis in a gut microbiota-dependent manner." (PMID 35761415, 2022). "In another study, a polysaccharide from Flammuliana velutipes (FVP) improved DSS-induced colitis via the regulation of colonic microbial dysbiosis and inflammatory responses by blocking the TLR4-NF-κB signal pathway, indicating that FVP is a potent agent for treating colitis." (PMID 36235004, 2022). "Given this background, our findings suggest that an internal link may exist between the suppression of inflammatory mediators, blocking of the TLR4/MyD88/NF-κB pathway, and restoration of intestinal barrier function in Jat ameliorate DSS-induced colitis." (PMID 36193153, 2022). "Furthermore, by blocking the TLR4/MyD88/GSK-3β/β-catenin/ROS/NF-κB loop, MT via the MT2-mediated pathway restored MUC2 depletion, ultimately alleviating the induced colitis in mice." (PMID 36421432, 2022). "Furthermore, protein expressions such as TLR4, MyD88, p–NF–κB-p65, NF-κB-p65, COX-2, ZO-1, and Occludin were detected to elucidate the molecular mechanism of Jat on DSS-induced colitis model." (PMID 36193153, 2022). "TLR4/NLRP3 plays key roles in regulating intestinal homeostasis, maintaining intestinal epithelial barrier integrity, and reducing mortality during experimental colitis and can also affect the composition of the intestinal biota." (PMID 33505499, 2021). "By comparison, in DSS-colitis ICR (institute of cancer research) mice, dietary supplementation with soy isoflavones (0.5% for 7 days) alleviated colitis severity and inactivated Myd88 but did not significantly alter TLR4 expression following colitis induction." (PMID 33916612, 2021). "TLR4 and MyD88 played a critical role in the development of DSS-induced colitis." (PMID 34925349, 2021).
colitis (continued). "The importance of the balancing role of TLR4 in intestinal injury and repair is also reported by Yun-Jie and colleagues, who found that moderate activation of TLR4 signaling both promotes inflammation and repairs the intestinal epithelium in DSS-induced colitis and radiation damage." (PMID 34112196, 2021). "In addition, melatonin attenuates TNBS-induced colitis through a melatonin receptor-independent pathway in mice and relieves TNBS colitis through the TLR4/MyD88/NF-κB signaling pathway in rats." (PMID 35116024, 2021). "Possibly, the high proportion of anti-inflammatory lactobacilli in the mucosa-adherent microbiome helped to curb the colitis severity despite the absence of TLR4 signaling." (PMID 33193406, 2020). "The essential oil and pericarp of ZBM have been demonstrated to have a positive impact on experimental colitis via the regulation of the NF-κ B/PPAR-γ and TLR4-related signaling pathways, respectively, suggesting its great potential to be a CAC-ameliorative candidate." (PMID 32410986, 2020). "TLR4 signaling in myeloid cells, particularly in pericryptal macrophages, is also required for the epithelial proliferative response in the repair phase of DSS colitis." (PMID 33552081, 2020). "According to researchers, flavonoids suppressed the activation of TLR-4/NF-κB p65 signaling pathway, leading to a decrease in gene expression of TNF-α, IL-1B, and IL-6, COX-2, TFF-3, and iNOS proteins in the intestinal mucosa in colitis model." (PMID 32848723, 2020). "Melatonin improved dextran sulfate sodium (DSS)-induced colitis and reverted microbial dysbiosis in wild-type (WT) mice but not in TLR4 knockout (KO) mice." (PMID 32042047, 2020). "TLR4 blockers are declared to have beneficial effects on acute gut inflammation, while it is known as an impeder for intestinal mucosal healing in DSS-induced colitis." (PMID 31780872, 2019). "In summing up, the main mechanism by which Gal-3 regulates immunosuppressive capacity of regulatory DCs in the gut is relied on the TLR-4-dependent activation of IDO-1/KYN pathway and consequent expansion of colon-infiltrated Tregs which suppress Th1 and Th17 cell-driven colon inflammation." (PMID 31336879, 2019). "We hypothesized that TLR4, which recognize the bacterial component LPS, could be involved heavily in lymphatic-driven inflammation and dysfunction during DSS induced colitis." (PMID 30972059, 2019). "During the onset of DSS-induced colitis, CD14/TLR4:LPS-dependent interaction between macrophages and bacteria, which have passed through DSS-injured colonic epithelium, results in the activation of NLRP3 inflammasome, which leads to the enhanced production of IL-1β in colonic macrophages." (PMID 31336879, 2019). "In addition, these in vitro results were correlated with colonic IL-6 levels in DSS colitis because DSS is thought to disrupt the integrity of the mucosal barrier, which allows commensal bacteria to elicit TLR2 and TLR4 dependent inflammation." (PMID 31921214, 2019). "In fact, the induction of colitis by DSS in the absence of TLR4, but not in the absence of TLR2, downregulated miR-146a expression." (PMID 30478292, 2018). "In terms of the activation/expression of receptors and signaling pathways in response to C. glabrata sensing and colitis, MBL-C and Myd88 expression increased significantly, while the expression of TLR-4 and PPARγ decreased in the colons in response to C. glabrata ΔChs3." (PMID 29463799, 2018). "However, the plant flavonoid alpinetin does improve DSS colitis through a similar mechanism of modulation of the NLRP3 and TLR4 pathways." (PMID 29515999, 2018). "Interestingly, the levels of TLR4 and TLR8 gene expression were previously increased when acute colitis was induced in pigs that had received a microbiota transplant from one pig breed but not another." (PMID 29577087, 2018).
colitis (continued). "The specific TLR4 inhibitor, TAK-242, significantly attenuated the severity of DSS-induced colitis in CK8+/− mice, suggesting that TLR4/NF-kB signaling may be involved in the inflammatory response to microbiota and may further promote tumor formation." (PMID 29228570, 2017). "Finally, we have assessed the influence of antibiotics and a toll-like receptor 4 (TLR4) inhibitor on CRC tumorigenesis and DSS-induced colitis, respectively, in CK8+/− mice." (PMID 29228570, 2017). "Here, we determined that BF bacteria alleviated DSS-induced colitis through the TLR2 receptor but not TLR4." (PMID 28683149, 2017). "In support, our very recent study revealed that TLR4 mediated PA induced inflammatory responses in otherwise healthy secondary abiotic IL10−/− mice without colitis." (PMID 29151895, 2017). "MOS administration attenuated colitis-related increase of Coliforms, normalized colonic muc2 expression and attenuated local expression of proinflammatory cytokines IL-1a, IL1b, IL6, KC, G-CSF and MCP1 as well as toll-like receptor TLR4 and NLRP3 inflammasome." (PMID 27658624, 2016). "For example, experimental studies in hosts knockout for TLR9, TLR4, and TLR2 have shown increased susceptibility to the development of a colitis induced by dextran sodium sulfate (DSS), as well as the protective role against DSS colitis induced by agonists of TLR2 and TLR4 supplement." (PMID 26090492, 2015). "Based on these findings, AC-mix may ameliorate colitis by the synergistic inhibition of IRAK phosphorylation and LPS binding to TLR4 on macrophages." (PMID 25276218, 2014). "It is noteworthy that HMGB1 specific receptors, TLR4 and RAGE, are up-regulated in colon tissues in colitis environment, implicating the importance of identifying a treatment strategy that will effectively sequester and neutralize different isoforms of HMGB1 in IBD." (PMID 25127031, 2014). "Here, we uncovered a novel mechanism whereby S. Typhimurium inhibits the expression of the transcription factor PPARγ in the host intestine, surprisingly without TLR-4 involvement; this inhibition worsened the severity of the host's colitis." (PMID 24465207, 2014). "Similar to the TNBS-colitis model, activation of both TLR2 and TLR4 is seen in IBD." (PMID 23382912, 2013). "Noteworthy, in comparison with C57BL6 wild type mice treated with TNBS, the colonic FXR expression was up-regulated in TLR2−/− but not in TLR4−/− mice, despite the colitis was less severe in these mice." (PMID 23372731, 2013). "Colitis induction resulted in increased expression of TLR2 and TLR4 in epithelial cells." (PMID 23382912, 2013). "In our study, the increase in adipose tissue inflammation seen in the Colitis + HFD group was confirmed by the increase in CLS, activated macrophages, lymphocytes and neutrophils and the overexpression of adhesion molecules, TNFα, IL-6, MCP1/CCL2 and TLR4." (PMID 22073943, 2011). "TLR4 and MyD88 knockout mice had distinctly less inflammation after chemical induction of colitis with dextran-sodium sulphate (DSS) as opposed to wild-type mice but grew Gram-negative bacilli more frequently from their mesenteric nodes." (PMID 21647408, 2011). "In the murine CAC model, we have described that TLR4 signaling is a dominant regulator of mucosal COX-2 expression and thus plays an important role in balancing mucosal production of PGE2 and 15d-PGJ2 during both the acute and chronic phases of colitis." (PMID 24212947, 2011). "This dual inhibition of TLR4 and RAGE, both of which contribute to NFκB activation, underscores the mechanistic superiority of the ALG-RSV-CSNPs formulation in controlling inflammation at multiple levels, leading to improved therapeutic outcomes in DSS-induced colitis." (PMID 40606616, 2025). "Furthermore, DM intervention markedly reduced TLR4/MyD88 protein abundance and NF‐κB phosphorylation (p < 0.05), confirming DM's inhibitory effect on TLR4/MyD88/NF‐κB pathway activation in DSS‐induced colitis." (PMID 40994452, 2025).